CSTB (cystatin B)
Diseases named in the same sentence as CSTB in open-access papers (continued):
Sharing a sentence is not in itself a finding about the gene and the disease.
tumor (27 papers, 2007 to 2026). "As the presence of CSTC is vital for the role of CSTB in tumour progression, CSTB was significantly associated with the prognosis in the CSTC high‐expression group rather than the CSTC low‐expression group in our in‐house PDAC cohort and TCGA." (PMID 36495123, 2022). "In our study on OSCC, CSTB expression was inversely related to the risk of aggressive tumor characteristics (i.e., lymph node metastasis, perineural infiltration, and lymphovascular invasion)." (PMID 34504787, 2021). "Collectively, these results indicated that ATRA exerts anti‐tumour activity in HCC by targeting the CSTB/CYTB axis, thereby impairing mitochondrial function and inhibiting tumour progression." (PMID 41578084, 2026). "Crucially, overexpression of CSTB in HepG2 cells partially rescued the tumour‐suppressive effects of ATRA." (PMID 41578084, 2026). "In conclusion, these results demonstrate that ATRA exerts its tumour‐suppressive effects, at least in part, through downregulation of CSTB." (PMID 41578084, 2026). "To evaluate the clinical significance of CSTB, we analysed CSTB expression levels across various tumour types using the UALCAN database." (PMID 41578084, 2026). "In subcutaneous tumor models in nude mice, the knockdown of CSTB resulted in smaller tumors in terms of size and weight, and a slower growth rate." (PMID 39996856, 2025). "The expression of CSTB was examined between tumor tissues and adjacent normal tissues obtained from iCCA patients via Western blot analysis." (PMID 39996856, 2025). "Previous studies have found that CSTB plays a significant role in a number of physiological and pathological processes, including protein metabolism, cell proliferation, apoptosis, and tumor metastasis." (PMID 39996856, 2025). "In vivo experiments demonstrated that the knockdown of CSTB reduced tumor volume, tumor weight, and growth rate." (PMID 39996856, 2025). "Tumor growth was observed to be more gradual in the CSTB knockdown group in comparison to the control group." (PMID 39996856, 2025). "The mean tumor weight was significantly lower in the CSTB knockdown group than in the control group." (PMID 39996856, 2025). "In epithelial ovarian cancer, elevated CSTB expression in ovarian tissue indicates tumor progression." (PMID 39996856, 2025). "For example, a recent study showed that CSTB secreted by macrophages can promote the migration and invasion of tumor cell." (PMID 37715019, 2023). "The bulk expression of CSTB and TM4SF1 was associated with both advanced tumor stage and poor PFS time in CRC patients." (PMID 36816947, 2023). "Surprisingly, we found a higher proportion of macrophage C4 in brain metastatic tissues, and this macrophage subpopulation was highly expressed in genes that promote tumor invasion and metastasis, such as CSTB, MMP9, CCL5, and MIF." (PMID 37715019, 2023). "Chi‐square analysis indicated that the expression of CSTB was significantly correlated with tumour differentiation." (PMID 36495123, 2022). "The average volume of tumours induced by CSTB knockdown was significantly smaller than that of the controls in the subcutaneous xenograft model." (PMID 36495123, 2022). "Poor overall survival and advanced tumour stages were strongly correlated with high expression of CSTB." (PMID 36495123, 2022). "IHC staining showed that a stronger PCNA intensity was observed in tumours induced by higher CSTB‐expressing cells." (PMID 36495123, 2022). "The expression of CSTB was positively related to the degree of tumor differentiation at the protein level (IHC)." (PMID 34504787, 2021). "The results showed that relative to normal samples, proteins (LAMC2, HMGA1, CSTB) were significantly upregulated in tumor tissues." (PMID 34732701, 2021). "As the expression trend of CSTB differs from tumor to tumor, the relationship between CSTB and prognosis is also inconsistent in different tumor types." (PMID 34504787, 2021).
tumor (continued). "Only one noninterventional study based on human OSCC tissue specimens reported that low expression of CSTB in the invasive tumor front was correlated with local tumor recurrence." (PMID 34504787, 2021). "There was little staining of CSTB in either the tumor stroma in OSCC or subepithelial tissues in control tissues." (PMID 34504787, 2021). "The increased CSTB expression in ovarian tissue represents tumor progression and is dysregulated by the TGF-β signaling pathway." (PMID 24452274, 2014). "Our data suggest that CSTB is tumor tissue-specific and overexpressed in ovarian borderline and malignant tumors." (PMID 24452274, 2014). "Finally, WB analysis of tumour lysates confirmed decreased expression of both CSTB and CYTB in the ATRA‐treated group, while CSTB overexpression attenuated this decrease." (PMID 41578084, 2026). "Finally, the observation that CSTB overexpression only partially reversed the tumour‐suppressive effects of ATRA suggests that ATRA likely exerts its anti‐HCC activity through mechanisms beyond the CSTB/CYTB axis." (PMID 41578084, 2026). "CSTB has been shown to promote tumour growth in the PyMT mouse model of breast cancer." (PMID 41578084, 2026). "Some previous studies have explored the specific mechanism by which CSTB affects tumor progression." (PMID 39996856, 2025). "In comparison to surrounding tissues, tumour tissues showed a higher expression of CSTB." (PMID 36495123, 2022). "SUVmax was significantly lower in tumours induced by CSTB‐knockdown cells." (PMID 36495123, 2022). "CSTB knockdown resulted in a remarkable decrease in tumour growth." (PMID 36495123, 2022). "Patients with lower expression levels of CSTB had shorter disease-free survival times and poorer clinicopathological features (e.g., lymph node metastases, perineural invasion, low degree of differentiation, and advanced tumor stage)." (PMID 34504787, 2021). "In WGCNA based on TCGA data, CSTB and tumor grade classification showed an indirect relationship at the gene level through the bridging role of the brown gene module; that is, the gene module most associated with CSTB expression was also the one most closely related to the phenotype of grade." (PMID 34504787, 2021). "The different expression patterns (i.e., different expression trends and inconsistent relationships with prognosis) of CSTB in tumors imply that CSTB could be a tumor-specific whistleblower." (PMID 34504787, 2021). "In addition, LAMC2, HMGA1 and CSTB were discovered to be upregulated significantly along with trajectory transition and elevated in the metastatic tumor lesions, which was consistent with published researches focusing on biological roles of LAMC2/ HMGA1." (PMID 34732701, 2021). "Although our study found differences in the content of CSTB in normal/OSCC cell culture supernatants, whether CSTB could be used to specifically identify tumor patients from the normal population is worthy of further research." (PMID 34504787, 2021). "These new findings indicated a similar tendency with our previous results on the cysteine–protease inhibitor, cystatin-B, that presented reduced levels in neoplastic islands from the invasive tumor front and also in the saliva of N+ OSCC patients compared with that in N0 OSCC patients." (PMID 33578082, 2021). "The majority of proteins (ACTR2, CSTB, LTA4H, PGK1, NDRG1, FSCN1, ITGAV, THBS2) significantly associated with clinical parameters showed lower expression in the ITF of the tumor stroma or neoplastic islands, with the exception of COL6A1, COL1A2, S100A8, S110A9, and MB." (PMID 30185791, 2018). "The results indicated that prioritized proteins, CSTB, NDRG1, PGK1, and ITGAV, may play a relevant biological role in tumor progression, since they were potentially associated, directly or indirectly, with patient prognosis." (PMID 30185791, 2018). "The protein levels of CSTB have been shown to correlate with tumor presence and stages." (PMID 26911362, 2016).
tumor (continued). "By comparison of CSTB expression associated with tumor size, the positivity of CSTB expression was not significantly different between small size (≤2 cm) and large size (>2 cm) of tumors (total and malignant, both P>0.05)." (PMID 24452274, 2014). "Future studies could evaluate the CSTB, PGK1, LTA4H levels in saliva according to recurrence and/or second primary tumor, which were relevant clinical data associated with their expression in the tissues and are also clinical challenges for therapeutic management in OSCC." (PMID 30185791, 2018). "CSTB protein levels were increased in both T1 and T3 stage HCC compared to normal tissue, with significantly higher levels observed in T3 stage tumours compared to T1 stage." (PMID 41578084, 2026). "To test the therapeutically benefit of CSTB on PDAC patients, we generated PDAC PDX murine models using tumour samples from three patients." (PMID 36495123, 2022). "Consistent with the results in the TCGA cohort, the mRNA expression of CSE1L, CSTB, MMP10 was significantly up-regulated in HCC while GYS2 was significantly down-regulated when compared with non-tumor tissues." (PMID 31139015, 2019). "Increased CSTB and NDRG1 expression was identified in the inner tumor, according to the MS discovery results, with staining only inside neoplastic cells of the OSCC, but in some cases, CSTB and NDRG1 were also detected in the adjacent normal epithelium." (PMID 30185791, 2018). "To investigate whether the tumour‐suppressive effects of ATRA are mediated through CSTB downregulation, we generated CSTB‐overexpressing (CSTBOE) HepG2 cells." (PMID 41578084, 2026). "Given the known tumour‐suppressive effects of all‐trans retinoic acid (ATRA) in solid tumours, this study investigated whether ATRA inhibits HCC progression by modulating CSTB expression." (PMID 41578084, 2026). "Notably, tumours overexpressing CSTBOE group exhibited significantly increased volume compared to control tumours, underscoring the critical pro‐tumorigenic role of CSTB." (PMID 41578084, 2026). "The findings supported our hypothesis and showed that CSTB was downregulated in OSCC compared with normal tissues, and this downregulation was related to worse clinical outcomes or signs of tumor malignancy." (PMID 34504787, 2021). "Among them, 13 proteins correlated with clinicopathological parameters and of these proteins, eight proteins were identified in neoplastic islands (ACTR2, CSTB, COL1A2, LTA4H, PGK1, NDRG1, S100A8, S100A9) and five proteins were identified in tumor stroma (COL6A1, FSCN1, ITGAV, MB, THBS2)." (PMID 30185791, 2018). "We speculated that resistant cells have nuclear localization of CTSL due to the lack of steffin B (CSTB), as evidenced in an advanced tumor microarray." (PMID 36291907, 2022). "Cystatin-B (CSTB), leukotriene A-4 hydrolase (LTA4H), protein NDRG1 (NDRG1), and phosphoglycerate kinase 1 (PGK1) from the neoplastic island dataset and collagen alpha-1(VI) chain (COL6A1), integrin alpha-V (ITGAV) and myoglobin (MB) from the tumor stromal dataset were prioritized." (PMID 30185791, 2018). "The immunoreactive staining of CSTB was negative in normal tissue, weak in benign tumor and strong in borderline and malignant tumors, which may represent tumor progression." (PMID 24452274, 2014). "Furthermore, we observed the overexpression of CSTB in benign and borderline tumors, comparing with normal tissue counterparts which appeared negative, suggesting that CSTB is tumor tissue-specific." (PMID 24452274, 2014). "Moreover, we found that the C4 subpopulation highly expressed cystatin B (CSTB), matrix metalloproteinase 9 (MMP9), chemokine C-C ligand 5 (CCL5), and macrophage migration inhibitory factor (MIF), which have the characteristics of promoting tumor cell migration and invasion." (PMID 37715019, 2023). "Two thirds of all 47-1 tumours showed a lack of amplification with multiple primers in the regions distal to PRSS7, proximal to TTC3, and distal to CSTB." (PMID 18047653, 2007).
cancer (23 papers, 2011 to 2026). A tumor composed of atypical neoplastic, often pleomorphic cells that invade other tissues. "Previous experimental evidence has consistently demonstrated dysregulated CSTB expression in association with multiple cancer types, suggesting its potential as an early diagnostic biomarker for HCC and ovarian epithelial tumours." (PMID 41578084, 2026). "Given the pivotal role of cathepsins in lysosomal proteolysis, an imbalance between CSTB and cathepsins frequently leads to impaired autophagy and is associated with various diseases, including cancer." (PMID 41578084, 2026). "Given the primary role of cathepsin in lysosome proteolysis, imbalance between CSTB and cathepsin often leads to impaired autophagy and is associated with multiple diseases including cancer." (PMID 36495123, 2022). "The roles of CSTB, a cysteine cathepsin inhibitor associated with various cancers, have been poorly understood, and few studies have focused on its association with HNSCC." (PMID 34504787, 2021). "Cystatin B (CSTB) functions as an inhibitor to suppress intracellular cysteine proteases and has been implicated in several types of cancers." (PMID 24452274, 2014). "Imbalance between CSTB and cathepsin is associated with multiple diseases including cancer." (PMID 39996856, 2025). "CSTB is associated with the pathogenesis of many malignant tumors." (PMID 38890346, 2024). "Similarly, cancer associated cystatin b gene was overexpressed in LPB-Tag mice as compared to CTRKO-LPBTag as well as CTRKO mice." (PMID 32180899, 2020). "The current study was undertaken to explore the expression of CSTB in human ovarian benign, borderline, and malignant tumors and investigate whether CSTB expression is associated with clinicopathological features of human EOC." (PMID 24452274, 2014). "Although the overexpression of CSTB in various cancers is observed, the mechanisms underlying the regulation of CSTB in cancer progression are unknown." (PMID 24452274, 2014). "However, most of the existing studies on the correlation between CSTB and tumors just provide observational evidence and whether CSTB has a causal role in cancers (including OSCC) is unclear." (PMID 34504787, 2021). "Analysis of the correlation between CSTB expression and HCC pathological stage revealed a significant association between high CSTB levels and advanced cancer stage." (PMID 41578084, 2026). "We detected high and low expressions of CSTB in cancer and adjacent tissues in the TCGA pan-cancer data, and found that CSTB is abnormally expressed in various tumors." (PMID 39996856, 2025). "CSTB is a protease inhibitor of cathepsin that is increased in cancer and acts as an intracellular thiol protease inhibitor." (PMID 35488257, 2022). "To explore the correlation between CSTB and the known cancer driver genes, we compared the DEGs obtained by cell line mRNA sequencing with the cancer driver gene set." (PMID 34504787, 2021). "CSTB was upregulated in most carcinomas (i.e., malignant tumors of epithelial origin), except for HNSCC and ESCC." (PMID 34504787, 2021). "The positive rate of CSTB expression was 100% in mucinous and clear cell tumors and 66.67% in serous tumor, including benign, borderline and malignant tumors." (PMID 24452274, 2014). "In the present work, we detected some AMPs (LTF, LZ and Cystatin B), which has numerous biological roles, including the modulation of immune responses, and has anti-microbial, anti-viral, anti-oxidant, anti-cancer, and anti-inflammatory activities." (PMID 38402260, 2024). "Aberrant expression of CSTB has been reported in several types of cancers." (PMID 36495123, 2022). "The role of CSTB in different types of cancers is controversial." (PMID 36495123, 2022). "However, our aim was to interpret the possible role of CSTB in cancer at the genetic level, and the results still provide innovative insights while exploring the functions of CSTB in OSCC." (PMID 34504787, 2021).
cancer (continued). "In the present study, significantly increased CSTB expression was noted in the cancer tissue, which might be related to the early stage of the cancer in our patient." (PMID 31692912, 2019). "CSTB is an inhibitor of cathepsin proteases, which are increased in cancer." (PMID 26911362, 2016). "Furthermore, by comparison of benign, borderline and malignant tumors, we observed that the immunoreactive score of CSTB protein was significantly higher in borderline and malignant tumors than that in benign tumors (both P<0.05)." (PMID 24452274, 2014). "A significantly higher level of CSTB was observed in the serum of PDAC patients, which was consistent with previous studies of several other types of cancer." (PMID 36495123, 2022). "The staining of CSTB was lighter in OSCC and showed preferential localizations in well-differentiated structures (i.e., cancer nests and keratinized pearls)." (PMID 34504787, 2021). "Second, the histological distributions of CSTB in HNSCC and ESCC are also consistent, that is, it is located in the epithelial structure of carcinoma tissues." (PMID 34504787, 2021). "Moreover, CSTB in serum could be used as a potential marker to distinguish PDAC patients from healthy people, which was consistent with previous studies of several other types of cancer." (PMID 36495123, 2022). "Finally, following the identification of cancer-related proteins CTTN, CSTB and CBS as novel proteomic targets of deoxyelephantopin, it is also tempting to speculate about potential biomedical application of synthetic analogues of this intriguing natural product as novel anticancer therapeutics." (PMID 27539788, 2016).
neurodegenerative disease (11 papers, 2014 to 2026). A disorder of the central nervous system characterized by gradual and progressive loss of neural tissue and neurologic function. "EPM1 is a neurodegenerative disease caused by bi-allelic partial loss-of-function mutations in the cystatin B (CSTB) gene, a potent and reversible inhibitor of cysteine cathepsins." (PMID 38179183, 2023). "KLK6 and CSTB have been suggested as biomarkers reflecting cardiovascular disease and neurodegenerative diseases." (PMID 34312731, 2021).
infection (7 papers, 2012 to 2025). The state of being infected such as from the introduction of a foreign agent such as serum, vaccine, antigenic substance or organism. "Cystatin B, an endogenous protease inhibitor, plays a critical role in regulating various physiological processes, particularly in modulating the host’s innate immune defense against pathogenic infections." (PMID 41017465, 2025). "After infection with the S. agalactiae and A. hydrophila, On-CSTB was significantly up-regulated in different tissues, especially in the organs rich in immune cells, like head kidney, spleen, and intestine." (PMID 41017465, 2025). "On-CSTB expression was significantly induced in different tissues following infection with A. hydrophila and S. agalactiae." (PMID 41017465, 2025). "Clathrin light chain and clathrin assembly protein PICA were only found in vacuolization stage, and the protease inhibitor cystatin B was increased in this infection stage." (PMID 33255149, 2020). "Down-regulated proteins included cystatin-B, dystroglycan, and mucin-1 in the early stage of infection (36 and 42 h PC), and myozenin-1 and alpha-lactalbumin at the subsequent stage (57 and 81 h PC)." (PMID 27412694, 2016). "Similar result could be observed that cystatin B from Pampus argenteus was found to be significantly up-regulated in the kidney after infection with Vibrio parahaemolyticus." (PMID 41017465, 2025). "We found that the levels of cystatin B and cystatin C in the culture fluids were similar in HIV-1 infected and uninfected MDM throughout the infection." (PMID 22693552, 2012).
cardiovascular disease (3 papers, 2017 to 2022). "Additionally, 32 TR genes (including GBP1, IFI30, CSTB, ACTR2, etc.)were found within risk loci of cardiovascular disease (Fisher’s exact test, P = 0.394)." (PMID 35133977, 2022).